MMP2 (matrix metallopeptidase 2)
Diseases named in the same sentence as MMP2 in open-access papers (continued):
Sharing a sentence is not in itself a finding about the gene and the disease.
ovarian carcinoma (continued). "High mRNA expression of MMP-2, MMP-9, MT1-MMP and TIMP-2 in primary ovarian tumors and stromal compartments was associated with poor survival in ovarian cancer patients, suggesting that MMP-2, MMP-9, MT1-MMP and TIMP-2 are valid markers of poor survival in advanced-stage ovarian carcinoma." (PMID 29393911, 2018). "Our current investigation was conducted to evaluate the curative effect of catalpol against ovarian cancer cells and explore whether its anticancer property is associated with modulations of miR-200 and MMP-2." (PMID 25347277, 2014). "In conclusion, the present study revealed that catalpol has antitumor activity for ovarian cancer cell lines and this effect may be associated with promoting the expression of miR-200 and restraining the expression of the MMP-2 protein signaling pathway." (PMID 25347277, 2014). "We hypothesized that Id1 is linked to the angiogenesis of ovarian cancer EPCs via regulation of the NF-κB/matrix metalloproteinase-2 (MMP-2) and PI3K/Akt pathways." (PMID 23714001, 2013). "Additionally, we have demonstrated that minocycline interferes with the metastatic potentials of ovarian cancer cells which was associated with suppression of MMP-2 and MMP-9." (PMID 23593315, 2013). "Similarly, the majority of the over 20 members of the MMP family including MMP-2 have been associated with tumor progression/aggressiveness in several cancers such as gastric, esophageal, breast, prostate, lung, bladder, and ovarian carcinoma." (PMID 28234925, 2017). "MMP14 was shown to activate pro-MMP2 to MMP2, playing a role in the development of vasculogenic-like networks and matrix remodeling by aggressive ovarian cancer cells." (PMID 40558552, 2025). "Others: GPC3 knockdown in ovarian cancer cells can lead to an increase in the expression of matrix metalloproteinase 2 (MMP-2) and MMP-9, along with a decrease in the level of tissue inhibitors of metalloproteinase 1 (TIMP-1)." (PMID 40422229, 2025). "The combination of the pan-PI3K inhibitor LY294002 with cisplatin effectively inhibits the proliferation and migration of ovarian cancer cells by downregulating the expression of Matrix Metalloproteinase-2 (MMP-2), TIMP1, and TIMP2." (PMID 40656893, 2025). "A Venn diagram revealed 30 overlapping targets between hydnocarpin and ovarian cancer, including key genes such as MMP2 and MMP9." (PMID 40722951, 2025). "Our results revealed that serum MMP-2 levels were lower in patients with malignant ovarian tumors than in those with benign tumors and controls." (PMID 41149076, 2025). "In osteosarcoma cells, nuclear MMP2 has been associated with cancer proliferation induction via histone H3 cleavage, and inactivation of the intracellular MMP2/p38 pathway suppressed angiogenesis and tumor growth in ovarian cancer cells." (PMID 39769278, 2024). "Higher MMP-2 concentrations were observed in the benign lesion (BL) group (median: 211.50 ng/mL) compared to the ovarian cancer (OC) group (median: 203.00 ng/mL, p = 0.12517), but this was not a statistically significant difference." (PMID 38892452, 2024). "Gelatinase MMPs such as matrix metalloproteinase − 9 (MMP-9) and matrix metalloproteinase − 2 (MMP-2) overexpression are associated with oral cancer, colorectal tumor, bladder carcinoma, retinoblastoma, pancreatic cancer, and ovarian cancer." (PMID 37798646, 2023). "The combination of both cisplatin and baicalein further significantly reduced the protein expression level of MMP2, and subsequently suppressed the metastasis of ovarian cancer cells." (PMID 37940982, 2023). "In this study, we found that the SMM extract reduced the expression levels of MMP-2/9 by inducing ROS accumulation in human ovarian cancer cells, resulting in reduced invasiveness of these cancer cells." (PMID 37507925, 2023).
ovarian carcinoma (continued). "While not as clear mechanistically, UGDH KD has also been shown to decrease expression of EMT transcription factors SNAIL, SIP-1, and matrix mellatoprotease protein 2 (MMP2) in ovarian cancer cell models." (PMID 37769033, 2023). "There is increasing evidence that RBP4 is associated with cancer development; for example, high levels of RBP4 promote the migration and proliferation of ovarian cancer cells through stimulation of MMP2 and MMP9 expression." (PMID 37313408, 2023). "After knocking down Snail, the activity of MMP-2 is greatly decreased, and the tumour size and metastasis rate of ovarian cancer were decreased, suggesting that Snail promotes the growth and metastasis of ovarian cancer by promoting MMP-2 activity." (PMID 37563232, 2023). "Increased levels of MMP-2 and MMP-9 are associated with the invasive and metastatic potential of malignant ovarian tumours." (PMID 37446252, 2023). "Previous studies have shown that SOX2 enhances the migration and invasion of laryngeal cancer cells and ovarian cancer cells through the upregulation of MMP2 expression." (PMID 36293387, 2022). "In ovarian cancer, the oncogenic effect of TP73-AS1 is associated with cell proliferation and metastasis through the matrix metallopeptidase 2/9 pathway." (PMID 35012518, 2022). "In ovarian cancer, VEGF-A has been linked to VM formation by elevating the expression of MMP-9, MMP-2, VE-cadherin, and EphA2." (PMID 35747793, 2022). "OMT was found to promote apoptosis and repress proliferation in ovarian cancer via upregulating miR-29b to reduce the level of MMP-2." (PMID 35609310, 2022). "quantified levels of two metalloproteinases (MMP-2 and MMP-9) and neutrophil gelatinase-associated lipocalin (NGAL) in urine samples collected from women with ovarian cancer and healthy controls." (PMID 35166350, 2022). "For example, lancemaside A, isolated from Codonopsis lanceolata, inhibits the metastasis of ovarian cancer cells and decreases the MMP2 and MMP9 expression levels." (PMID 35621926, 2022). "Luteolin had been reported to inhibit ovarian cancer metastasis by downregulating MMP2 (Matrix Metallopeptidase 2) and MMP9 (Matrix Metallopeptidase 9)." (PMID 36483919, 2022). "In fibroblasts treated with exosomes from untreated ovarian cancer cells, a more significant increase in MMP2 and MMP10 expression was observed for the exosomes derived from the TOV-21G lineage." (PMID 36012171, 2022). "In a 3D organotypic model of ovarian cancer, it was found that MMP-2 plays a role in adhesion during the first steps of metastasis." (PMID 36077825, 2022). "Abdominal ascites in ovarian cancer patients is enriched in MMP-2, -9, and -14 which play a major role in peritoneal dissemination." (PMID 35047406, 2021). "We further evaluated the effect of ERK activation by CCL7 on the expression of MMP-2 and -9, which play critical roles in ovarian cancer metastasis." (PMID 34206004, 2021). "Previous studies revealed that the PI3K/Akt pathway can upregulate the secretion of metalloproteinase (MMP)-2 and -9 to enhance the invasion ability of ovarian cancer cells." (PMID 34445559, 2021). "Reports show that MMP-2 is highly expressed in cancers such as ovarian cancer, renal cell carcinoma, and prostate cancer, leading to poor survival of patients." (PMID 34027107, 2021). "We detected the content of MMP-2 in epithelial ovarian cancers cells with interfered and overexpressed FBXO22." (PMID 34950036, 2021). "For example, MMP-2 mRNA expression was significantly higher in ovarian cancer cells that was sensitive to chemotherapy compared with resistant/refractory tumors, while no significant change in MMP-9 mRNA expression was noted." (PMID 35047406, 2021). "Subpopulation of MMP9+/MMP2+/EMMPRIN+ at the surface of blood plasma exosomes in high-volume ascites ovarian cancer patients was reduced compared to that in low-volume ascites patients." (PMID 33773551, 2021).
ovarian carcinoma (continued). "In this study, both ST09 treated ovarian cancer cell lines showed downregulation of MMP1, MMP2, and MMP9 with DDR1 loss." (PMID 34837026, 2021). "Histological analysis of tumor tissue indicated that luteolin suppressed proliferation and migration in ovarian cancer cells via downregulating the expression of matrix metalloproteinase 2 (MMP2) and MMP9." (PMID 34594472, 2021). "It was reported that MMP2 expression was higher in benign tumors than in borderline and malignant tumors of ovarian cancer, and the cells were sensitive to chemotherapy." (PMID 35664989, 2021). "The growth and spread of ovarian cancer can be orchestrated by MMP-14 in conjunction with other molecules including MMP-2, TIMP-2 and the integrins." (PMID 34344453, 2021). "CQDs/Cu2O selectively mediated of ovarian cancer SKOV3 cells death mainly through downregulation the expression of MMP-2, MMP-9, F-actin, and VEGFR2, meanwhile CQDs/Cu2O induced apoptosis of SKOV3 via S phase cell cycle arrest." (PMID 33663548, 2021). "In conclusion, FBXO22 promotes the growth and metastasis of epithelial ovarian cancers cells via the MMP-2 and MAPK pathways." (PMID 34950036, 2021). "Norepinephrine and E can directly increase the invasive ability of ovarian cancer cells through upregulation of MMP-2 and MMP-9 via ADRB2." (PMID 34307378, 2021). "The role of VEGF-VEGFR in invasion and migration of ovarian cancer is proven in vitro through the secretion and activation of Matrix Metalloproteinase-2 (MMP-2), MMP-7, MMP-9 and urokinase type plasminogen activators." (PMID 33639643, 2021). "Paclitaxel-resistant ovarian cancer cells not only enhanced invasion and migration but also increased the expression of MMP2 and 9 in inducing the overexpression of EIF4G2 when compared to SiRNA- SNHG7 group." (PMID 34709112, 2021). "MMP-2 was reported as an early regulator of metastasis, and uPA was reported to promote metastasis in ovarian cancer cells." (PMID 32934709, 2020). "Consistent with our results, silencing of ECE1 in ovarian cancer cells has been shown to decrease ET‐1 production, MMP‐2 activity, and invasiveness." (PMID 31788944, 2020). "Firstly, ovarian cancer tissue showed an increased protein expression of Notch1, Snail, MMP-2, N-cadherin and Vimentin, but had decreased expression of E-cadherin." (PMID 32547317, 2020). "Specifically, our study findings are in line with a recent study showing that two bioactive compounds of pomegranate namely ellagic acid and luteolin prevent proliferation and migration of ovarian cancer cells by reducing the expression of MMP-2 and MMP-9." (PMID 32224968, 2020). "We demonstrate that T2-KD cells are associated with increased expression of MT1-MMP and decreased expression and activity of MMP-2 in ovarian cancer and Fallopian tube epithelial cells." (PMID 33023532, 2020). "The chromatin remodeling protein BRG1 has been demonstrated to mediate MRTF-A-dependent trans-activation of MMP2 gene in ovarian cancer cells." (PMID 32999272, 2020). "Studies have shown that activation of STAT3 in ovarian cancer leads to upregulation of MMP2 expression, and inhibition of STAT3 in pancreatic cancer cells results in down-regulation of MMP9 expression." (PMID 33292347, 2020). "It is certain, however, that ovarian carcinomas showed significantly higher levels of MMP-2 than benign and borderline tumors." (PMID 32751899, 2020). "Ovarian cancer tissue had increased expression of Notch1, Snail, MMP-2, N-cadherin and Vimentin, but had decreased expression of E-cadherin." (PMID 32547317, 2020). "With regards to the role of quercetin in anti-metastasis, one study revealed that 3,4′,7-O-trimethylquercetin inhibited the invasion and metastasis of ovarian cancer cells by decreasing the expression of MMP-2 and urokinase plasminogen activator (uPA)." (PMID 32934709, 2020).
ovarian carcinoma (continued). "By using siRNA, we examined the effect of TIMP-2 knock down (T2-KD) on MT1-MMP and MMP-2 expression levels, proliferation, invasion and chemosensitivity in Fallopian tube secretory epithelial cells and two ovarian cancer cell lines." (PMID 33023532, 2020). "Inhibition of MMP2 in ovarian cancer cells inhibited their adhesion to peritoneal surfaces in nude mice." (PMID 32780245, 2020). "Our study showed that LPS and IL-8 stimulated UCB-derived neutrophils increased E-cadherin expression and decreased N-cadherin, MMP-2 expression in ovarian cancer cells." (PMID 32489460, 2020). "Overexpression of miR-615-5p or miR-6753-5p reversed the upregulation of NF-κB or MMP2 in cells overexpressing circPUM1, which suggests that circPUM1 mediates its carcinogenic effects by regulating the expression of these oncogenes in ovarian cancer." (PMID 31751911, 2019). "This suggests that VEGF-A interacts with the VE-cadherin/EphA2/MMP-2/Ln5γ2 axis in the regulation of VM in ovarian cancer." (PMID 31612116, 2019). "A meta-analysis demonstrated that MMP-2 expression was higher in ovarian cancer tissue than that in benign or normal ovarian tissue." (PMID 29949618, 2018). "Until now, well known MMPs which levels correlate with ovarian cancer are levels of MMP2, MMP7 and MMP9." (PMID 29304854, 2018). "In another independent study, MMP-2 level was positively correlated with clinical stage and metastasis of ovarian cancer patients." (PMID 29393911, 2018). "Still, sequential detection of serum MMP-2 has been suggested as a strategy for assessing the chemotherapy response in optimally operated patients with ovarian cancer." (PMID 29949618, 2018). "MMP expression, particularly MMP-2 and MMP-9, has been shown to have clinical association with progression of ovarian cancer." (PMID 29891015, 2018). "In ovarian cancer, ascites rich in MMPs; MMP-2, -9, and -14 are major contributors to peri-cellular proteolysis in the peritoneal microenvironment." (PMID 29393911, 2018). "Increased activity of MMP‐9 was observed in both the ovarian cancer cells, whereas MMP‐2 activity was increased only in PA‐1 cells, as shown by gelatin zymography." (PMID 28236660, 2017). "Since the invasion and metastasis of tumors largely depend on the degradation of ECM, expression of MMP-2 plays a positive role in the progression of ovarian cancer." (PMID 28538838, 2017). "Fe-MIL-101 suppresses the proliferation of human SKOV3 ovarian cancer cells via downregulation the expression of MMP-2 and -9." (PMID 28538838, 2017). "Exposing vesicles released by ovarian cancer cells (CABA1) to acidic medium increased MMP-2 and MMP-9 activities; this effect was abolished by the specific inhibitor of cystein protease or by silenced expression of cathepsin B in CABA1 cells." (PMID 28317069, 2017). "Serous ovarian carcinoma which was used as a positive staining control showed intense MMP-2 expression." (PMID 28234925, 2017). "Overexpression of HIF‐1α upregulated AEG‐1 expression and enhanced migration of ovarian cancer cells by inducing the expression of MMP2 and MMP9 as well as inhibiting the expression of E‐cadherin and β‐catenin." (PMID 28401704, 2017). "This suggests that miR-519d has suppressive effects on ovarian carcinoma by downregulating RhoC, Bcl-2, cyclin D1, survivin, MMP2, MMP9, STAT3 and HuR expression." (PMID 28146423, 2017). "Bisdemethoxycurcumin inhibits ovarian cancer cells via reducing oxidative stress-mediated expression of MMP-2 and -9." (PMID 28538838, 2017). "An inhibitor of MMP2 has been shown to significantly increase cytotoxicity in cisplatin-resistant ovarian carcinoma cell line A2780cis." (PMID 28800781, 2017). "MMPs are correlated with ovarian cancer, with the levels of MMP-2, MMP-7 and MMP-9 elevated in ovarian cancer patients." (PMID 28957437, 2017). "Catalpol suppressed proliferation and accelerated apoptosis of OVCAR-3 ovarian cancer cells via promoting microRNA-200 expression and reducing MMP-2 signaling." (PMID 28538838, 2017).
ovarian carcinoma (continued). "Oestradiol has been found to increase the metastatic potential of human epithelial ovarian cancer cell through the upregulation of MMP-2 and downregulation of E-cadherin." (PMID 28717394, 2017). "Several studies have attempted to explore the role of MMP-2 as a therapeutic target for ovarian cancer." (PMID 28538838, 2017). "Catalpol suppresses proliferation and accelerated apoptosis of OVCAR-3 ovarian cancer cells via promoting microRNA-200 expression and reducing MMP-2 signaling." (PMID 28538838, 2017). "It has been reported previously that pro-MMP-2 activation is induced by clustering of integrin in ovarian cancer cells." (PMID 28270508, 2017). "Zoledronic acid exerts robust inhibitory activity on cell invasion of HeyA8-MDR and OVCAR-5 ovarian cancer cells through decreasing the intracellular level of MMP-2." (PMID 28538838, 2017). "Our findings suggest that E2F1 functions as an oncogene in ovarian carcinoma in part by upregulating Bcl-2, cyclin D1, survivin, MMP2, and MMP9 expression." (PMID 28146423, 2017). "Our results suggested that HIF‐1α binds to AEG‐1 promoter to upregulate its expression, which was correlated with metastasis in ovarian cancer by inducing the expression of MMP2 and MMP9 as well as inhibiting expression of E‐cadherin and β‐catenin." (PMID 28401704, 2017). "Recent data also suggested that C3G, acting through Rap1, induces invasion of epithelial ovarian cancer cells and promotes the secretion of matrix metalloproteases MMP2 and MMP9." (PMID 27286263, 2016). "In vivo work using a murine model of ovarian cancer showed that chronic behavioural stress was associated with increased tumour growth and vascularisation and enhanced expression of VEGF, MMP-2 and MMP-9." (PMID 27899953, 2016). "Recent published data also suggest that C3G, acting through Rap1, promotes invasion of epithelial ovarian cancer cells through induction of MMP2 and MMP9 secretion." (PMID 27286263, 2016). "The aim of the present study is to evaluate the prognostic value of MMP-14 and MMP-2 expression in ovarian cancer, as determined by semi-quantitative immunohistochemistry, in a large regional cohort." (PMID 27038607, 2016). "It was confirmed that uPA promoted VM formation through AKT/mTOR/MMP-2/Laminin5γ2 signal pathway in ovarian cancer." (PMID 26992227, 2016). "This study was designed to determine the prognostic value of MMP-14 and MMP-2 expression in ovarian cancer with data on long-term follow-up." (PMID 27038607, 2016). "In ovarian cancer, overexpression of MMPs such as MMP-2, MMP-7, MMP-9, MMP-11 and MMP-14 has been reported and correlated with invasion and metastasis." (PMID 27038607, 2016). "The mean value of MMP-2 in ovarian cancer patients increased remarkably (75.87±18.82 ng/ml) as compare to healthy controls (32.58±7.18 ng/ml)." (PMID 27902750, 2016). "Combined with our results, we first validated that uPA had important positive role on the VM formation by regulating AKT/mTOR/MMP-2/Laminin5γ2 signal pathway in ovarian cancer." (PMID 26992227, 2016). "All of these results suggested that uPA was a positive mediator for VM formation in ovarian cancer via AKT/mTOR/MMP-2/Laminin5γ2 signal pathway." (PMID 26992227, 2016). "MMP-14 and MMP-2 also appear to be overexpressed in serous and mucinous malignant ovarian tumor epithelium, while benign and borderline tumors show lower levels of expression." (PMID 27038607, 2016). "Studies have found that MMP2 levels in ascites fluid increase in advanced stage ovarian cancer and overexpression of MMP2 in peritoneal implants correlates with elevated mortality risk." (PMID 26648788, 2015). "MMP2 has been shown to play a major role in mediating ovarian cancer cell attachment to the omentum and enabling tumor cells to invade through the extracellular matrix to establish further metastases." (PMID 26648788, 2015).